IL1B (interleukin 1 beta)
Diseases named in the same sentence as IL1B in open-access papers (continued):
Sharing a sentence is not in itself a finding about the gene and the disease.
Arthritis (continued). "Andrographolide treated CFA-induced arthritis by inhibiting the expression of a series of arthritis-related molecules, including COX-2, NF-κB, p-p38, CD40, TNF-α, IL-1β, and IL-6." (PMID 36238575, 2022). "ApoB was reported to aggravate arthritis by eliciting the production of TNF-α, IL-1β, and IL-6 through p38 mitogen-activated protein kinase and NF-κB pathways." (PMID 34996506, 2022). "In collagen II-induced arthritis male DBA/1J mice, ginkgolide B (10, 20, and 40 μM, i.p., for 43 days) decreased the serum levels of IL-1β, IL-6, TNF-α, MMP-3, and MMP-13 and increased the anti-inflammatory cytokine IL-10." (PMID 35368757, 2022). "And, IL-37 treatment ameliorates temporomandibular joint inflammation via inhibiting the expression of NLRP3 and IL-1β, which can be reversed by knockdown of IL-1R88." (PMID 36418383, 2022). "When treating complete Freund’s adjuvant-induced arthritis, AG inhibits a series of molecules related to arthritis, such as cyclooxygenase-2 (COX-2), NF-κB, p-p38, CD40, TNF-α, IL-1β, and IL-6." (PMID 36188549, 2022). "Significant increases in all inflammatory markers in MUS-induced arthritis in rats compared to controls, with percentage increases of 678.64, 982.62, and 203.03% for TNF -α, IL-1β and NF-κB, respectively." (PMID 36286462, 2022). "These mice developed less incidence of arthritis, decreased clinical arthritis scores, synovitis and had less pro-inflammatory synovial cytokines levels (TNF, IL-1β, IL-6)." (PMID 35455985, 2022). "Pro-inflammatory markers TNF-α, NF-κB, IL-6, IL-1β, and COX-2 were significantly downregulated with piroxicam, EEJR, and NHJR in comparison with the arthritis group." (PMID 35422870, 2022). "In the collagen induced arthritis model, treatment with MCC950, a selective inhibitor of NLRP3, reduces IL-1β, synovial inflammation and cartilage erosion." (PMID 33605409, 2021). "IL-1β and iNOS were selected to verify the mRNA results, and COX-2 was selected as an important biomarker of arthritis." (PMID 34361701, 2021). "TQ (5 mg/kg body weight) significantly downregulated the level of pro-inflammatory mediators (IL-1b, IL-6, TNF-α, and prostaglandin E2) to reduce arthritis scoring and bone leaching in collagen-induced arthritis in a Wistar rats in vivo model." (PMID 34067322, 2021). "Resveratrol inhibits the activation of the MAPK signalling pathway and the expression of IL-1β in synovial tissues of CIA rats and exerts a positive regulatory effect on the development of arthritis." (PMID 34887866, 2021). "On the other hand, whereas IL-1β was shown to be important for the development of CIA and K/BxN serum transfer arthritis, blocking this pro-inflammatory cytokine during AIA did not decrease the inflammation in this model." (PMID 34412663, 2021). "The activities of proinflammatory cytokines interleukin 1 beta (IL-1β), IL-6 and tumor necrosis factor alpha (TNF-α) contribute to the pathogenesis of arthritis by promoting proteolytic enzyme activity that damages the cartilage extracellular matrix." (PMID 34198264, 2021). "For example, in the acute K/BxN serum-induced arthritis model, signalling via TLR4-MyD88, as well as IL-1α and IL-1β activity, play a more crucial role in disease progression and chronicity than TNF itself." (PMID 33924766, 2021). "Delivery of MSU into the abdominal cavity and the joints resulted in NLRP3-dependent IL-1β production and neutrophil influx and NLRP3-dependent arthritis, respectively." (PMID 34745110, 2021). "Specifically, in models of acute arthritis, proteinase 3 from neutrophils can cleave pro-IL-1β and MAC deposition is known to be elevated in the context of arthritis." (PMID 34650553, 2021). "The WT, Faslpr/lpr, and Fas–/– mice developed autoantibody-induced arthritis (AIA), whereas the Faslgld/gld mice exhibited attenuation of joint swelling and expression of Il6, Tnfa, Il1b, Ccl2, and Ccl3." (PMID 34223817, 2021).
Arthritis (continued). "Previous studies have suggested that isorhamnetin attenuates collagen-induced arthritis via modulating the levels of cytokines TNF-α, IL-1β, and IL-6 etc. in the joint tissue homogenate of mice." (PMID 32754034, 2020). "TGs, which derived from botanical materials, exhibits immune-suppressive functions, and also attenuates inflammation and arthritis through reducing PGE2 production and levels of IL-1α, IL-1β, TNF-α and IL-6." (PMID 32503513, 2020). "After administration, the levels of IL-6, IL-1β, and TNF-α decreased, and the arthritis detumescence percentages increased significantly, and the bony erosion degree was distinctly decreased in the TP-CMCS groups and TP group." (PMID 32110979, 2020). "The significant decrease in the levels of TNF-α, IL-1β, and IL-6 confirmed a positive effect of rhoifolin on alleviating inflammation in CFA-induced arthritis." (PMID 32401927, 2020). "Adoptive transfer of ILC2s attenuated murine arthritis severity, and ILC2-derived IL-4/13 inhibited IL-1β and TNFα secretion by macrophages, which indicated the immunoregulatory function of the IL-4/13-producing ILC2 subset in RA." (PMID 33072104, 2020). "The pharmacological study on madecassoside demonstrated that it can effectively lessen the related inflammatory factors in arthritis model rats (TNF-α ↓, IL-1b ↓, IL-6 ↓, IFN-γ ↓, IL-17 ↓)." (PMID 33013406, 2020). "Together these studies demonstrate that in arthritis, local 11β-HSD1 expression and activity is under the regulatory control of the pro-inflammatory microenvironment, driven by TNF-α and IL-1β." (PMID 32963891, 2020). "Oral intake of a mixture of Acacia catechu water extract and Morus alba root bark ethanol extract (50 mg/kg BW) has anti-inflammatory (TNF-α and IL-1β), collagenase (MMP-13) inhibitory, and articular cartilage protective activities in MIA-induced arthritis." (PMID 33371279, 2020). "We found that expression levels of IL-1β, IL-6, TNFα, CCL3 and MCP-1 molecules were significantly (p < 0.05) increased after induction of arthritis in the bone marrow of KLF2+/− mice compared to KLF2+/+ mice." (PMID 31426355, 2019). "SM significantly improved arthritis symptoms; increased the level of OPG; inhibited the levels of TNF-α, IL-1β, CRP, ATX, and LPA; and alleviated cartilage and bone injury." (PMID 31001354, 2019). "HDAC6 inhibitor, CKD-L decreased the arthritis score in collagen-induced arthritis model and reduced the expression of TNF-α and IL-1β in rheumatoid arthritis patients." (PMID 30841513, 2019). "Similarly, IL-1β stimulated Wnt5a expression through activation of NF- κB and the subsequently overexpression of p65 in chondrocytes, while BAY11–7082, a specific inhibitor of IκBα-phosphorylation, abrogated the induction of Wnt5a by IL-1β in the cartilage destruction caused by arthritis." (PMID 31420042, 2019). "SM significantly alleviated arthritis symptoms, inhibited bone erosion, and decreased the levels of TNF-α, IL-1β, CRP, ATX, and LPA in the sera of CIA rats." (PMID 31001354, 2019). "Mechanism studies have confirmed that A2AR activation attenuates progression of experimental arthritis by inhibiting TNF-α and IL-1β production, both of which are the key pro-inflammatory cytokines in the pathogenesis of inflammation flare." (PMID 30679935, 2019). "QZTB suppressed the serum IL-1β (P < 0.01) and TNF-α (P < 0.001) levels in the MSU crystal-induced rats, suggesting that QZTB can inhibit NLRP3 pathways contributing to arthritis in this acute gout model." (PMID 31885675, 2019). "After treated with enrofloxacin, significant alteration in cytokine expressions were detected, including higher levels of IFN-γ and IL-17A in arthritis model mice and higher TNF-α, IL-1β levels in chicken models." (PMID 31069173, 2019). "Rats treated with UP1306 showed statistically significant improvements in arthritis severity markers, including uCTX-II (91.4% vs. collagen-induced arthritis (CIA)), serum IL-1β, TNF-α, and IL-6 levels as well as synovial MMP-13." (PMID 30691120, 2019).
Arthritis (continued). "In the present study, a collagen-induced arthritis rat model, IL-1β-stimulated SW982 cells, and RA-like fibroblast-like synoviocytes (FLS) were employed to investigate the effect and possible mechanism of osthole on arthritis in vivo and in vitro." (PMID 29743895, 2018). "It is evident that the first phase of arthritis is accompanied with the release of mediators such as histamine and proinflammatory cytokines, particularly TNF-α and IL-1β." (PMID 30719247, 2018). "b and c Mean ± SEM of IL-1β and TNF-α in synovial tissue extracts from mice subjected to experimental zymosan-induced arthritis and treated with OLT1177 (600 mg/kg) (n = 4 per group)." (PMID 30075804, 2018). "Psoralen was reported to treat arthritis by regulating the balance of Th1/Th2 cells and inhibiting the expression of TNF-α, IL-6, and IL-1β." (PMID 29922598, 2018). "In conclusion, in the cell interactions as found in arthritis, Cd induced an increased TNF-α/IL-1β ratio, resulting in an active import and storage of Cd inside the cell." (PMID 29768427, 2018). "CKD-L decreased the arthritis score in CIA, reduced the expression of TNF and IL-1β, and increased the expression of IL-10 in PBMC from RA patients." (PMID 28673326, 2017). "We also provide evidence that tobramycin-sensitive indigenous commensal intestinal bacteria contribute to arthritis in IL1rn−/− mice and identify a significant role for TLR4 in mucosal induction of IL-1β and IL-17 prior to the onset of arthritis." (PMID 28645307, 2017). "After injection with complete Freund's adjuvant, body weight, arthritis score, and the serum levels of TNF-α, IL-1β, IL-6, myeloperoxidase (MPO), malondialdehyde (MDA), superoxide dismutase (SOD), and glutathione peroxidase (GSH-PX) were assessed." (PMID 28491105, 2017). "CKD-L, a selective HDAC6 inhibitor, decreased the arthritis score in CIA, reduced the expression of TNF and IL-1β, and increased the expression of IL-10 in PBMC from RA patients." (PMID 28673326, 2017). "Our data demonstrated that CKD-L, a selective HDAC6 inhibitor, decreased the arthritis score and protected against joint destruction in the CIA model, and reduced the expressions of TNF and IL-1β, and increased the expression of IL-10 in PBMC from RA patients." (PMID 28673326, 2017). "Several studies found that the expression of IL-1β, NO, and PGE2 is significantly increased in arthritis tissue and OA animal models, even in patient serum." (PMID 28167976, 2017). "For instance, phosphatidylserine inhibits inflammatory responses in IL-1β-stimulated FLS and alleviates carrageenan-induced arthritis in rats." (PMID 28569176, 2017). "In the present study, we demonstrated that plasma levels of IL-1β and TNF-α correlated with ED throughout the arthritis course." (PMID 26761790, 2016). "Transfer of IL-17-deficient donor bone marrow into CIA DBA/1J mice inhibits development and severity of clinical arthritis, due to reduction in the secretion of the pro-inflammatory cytokines TNF-α, IL-1β and IL-6." (PMID 26634933, 2016). "In the present study, IL-1β (10 ng/ml) promoted 80 pg/ml FGF-2 expression in chondrocytes; this result is consistent with severe arthritis patients in the clinic." (PMID 26811540, 2016). "In arthritis of SKG mice, GM-CSF secreted by T cells upregulated the production of pro-inflammatory cytokines such as IL-6 or IL-1β from macrophages." (PMID 29259681, 2016). "IL-1β increases the synthesis of COX-2, which plays a significant role in the overproduction of prostaglandin E2, thereby leading to arthritis." (PMID 27881135, 2016). "In another study, CI-1040 reduced IL-1β production and ECM alterations in a mouse model of arthritis." (PMID 25550395, 2015). "Proinflammatory cytokines, namely IL-1β, IL-6, IL-17 and TNF act synergistically to maintain inflammation and bone erosions in animal models of arthritis and in RA patients." (PMID 26658436, 2015).
Arthritis (continued). "Ameliorative efficacy of TSE was evaluated on arthritis induced inflammation quantitatively by determining the serum levels of TNF-α, IL-1β, IL-6 and IL-10 using ELISA kits." (PMID 26059174, 2015). "Based on the results of a recent drug screen for compounds that simultaneously inhibit IL-1β and TNF secretion, we chose gambogic acid as a promising therapeutic candidate for the treatment of arthritis." (PMID 24623960, 2014). "During autoantibody-induced arthritis, the recruitment of neutrophils in the inflamed joint requires a cascade of cytokines and chemokines (LTB4, IL-1β, CCR1, and CXCR2 ligands) produced by endothelial cells, synovial cells, and neutrophils themselves." (PMID 24968718, 2014). "The degree of toe swelling, arthritis index, spleen index, and the expression levels of tumor necrosis factor (TNF)-α, interleukin (IL)-1β and IL-6 were measured." (PMID 25289073, 2014). "We have selected gambogic acid as a promising therapeutic candidate for the inhibition of both IL-1β and TNF secretion, due to the reduction in caspase-1 and NF-κB activation, and consequently for the treatment of arthritis." (PMID 24623960, 2014). "Asarum extract was found to significantly reduce the severity of arthritis by decreasing hind paw swelling, the arthritis index, the spleen index, and TNF-α, IL-1β and IL-6 expression levels in plasma." (PMID 25289073, 2014). "Curcumin treatment downregulated clinical arthritis score, proliferation of splenic T cells, expression of TNF-α and IL-1β in the ankle joint, and serum IgG2a levels." (PMID 23476694, 2013). "IFN-γ also inhibits IL-1b-mediated production of MMP-1 and MMP-3 by synovial fibroblast in the early phase of arthritis." (PMID 23613752, 2013). "The pro-inflammatory cytokines such as IL-1β and TNF-α, produced by the activated macrophages and T cells, appear to be involved in the perpetuation of arthritis." (PMID 23971042, 2013). "Interestingly, blockade of TNFα reduces joint inflammation while inhibition of IL-1β protects against cartilage degradation in mouse arthritis models, suggesting the latter may be an attractive molecular target in the development of disease-modifying therapies." (PMID 23889808, 2013). "IL-1β, IL-6, IL-17, and TNF are found to be elevated during the development of arthritis, and inhibition of TNF and IL-6 represent successful treatments of RA." (PMID 24286140, 2013). "We aimed to investigate the effects of IL-1β/HMGB1 complexes on mPGES-1 and other enzymes of the PGE2 pathway in synovial fibroblasts (SFs) from patients with arthritis." (PMID 23488692, 2013). "Compared to wild type (WT) mice, TLR4-/- mice showed attenuated arthritis and low interferon (IFN)-γ, IL-12p35 and IL-1β transcript levels in the joints, but high transforming growth factor (TGF)-β expression." (PMID 23036692, 2012). "To confirm the functional involvement of individual cytokines in TLR4-mediated arthritis, we injected i.p. recombinant IFN-γ, IL-12 or IL-1β into TLR4-/- mice during antibody-induced arthritis." (PMID 23036692, 2012). "Prior studies have shown that macrophages derived from NMU-KO mice produced normal levels of IL-1β and TNF, critical arthritogenic cytokines in K/BxN serum-transferred arthritis and also IL-12p40 following lipopolysaccharide stimulation." (PMID 22314006, 2012). "For therapeutic purposes, it would be beneficial to inhibit TLR4 signals, IL-12 production, and the effects of IL-12 on IL-1β and IFN-γ production in antibody-induced joint inflammation." (PMID 23036692, 2012). "Taken together, these results suggest that TLR4-mediated IL-12 production by macrophages, mast cells and Gr-1+ cells enhances joint production of IFN-γ and IL-1β, which suppresses TGF-β production, and thereby promotes antibody-induced arthritis." (PMID 23036692, 2012).
Arthritis (continued). "We showed that arthritis was characterized by an early transcriptional activation of the chemokine MCP-1, the proinflammatory cytokines IL-1β, IL-6, and TNFα, and the angiogenic factor VEGF in synovial tissue." (PMID 22414623, 2012). "TLR4-mediated IL-12 production by joint macrophages, mast cells and Gr-1+ cells enhances IFN-γ and IL-1β production, which suppresses TGF-β production, thereby promoting antibody-induced arthritis." (PMID 23036692, 2012). "IL-1β-induced JNK and p38 MAPK are critical in the induction of MMPs and subsequent tissue destruction in arthritis." (PMID 21835002, 2011). "Local treatment with HpTNFR1 markedly reduced mRNA and protein levels of interleukin (IL)-1β and IL-6 in SLC during SCW arthritis and ameliorated CIA." (PMID 20370892, 2010). "In murine AIA, significant and temporal changes in cytokines (IL-1β, TNFα, IFN-γ, IL-6) and factors that govern extracellular matrix turnover (MMP-3, MMP-13, TIMP-1) occur during the acute phase, Days 1 to 3 after arthritis induction." (PMID 20307272, 2010). "An imbalance of IL-1β and IL1-RN signalling has been proposed as an important factor in several inflammatory conditions in man such as asthma and arthritis." (PMID 20670446, 2010). "To determine the effects of inflammatory cytokines during the effector phase of arthritis, we measured the serum concentrations of TNF-α, IL-6, IL-1β, and IFN-γ at days 0, 7, 14, and 28 in DBA/1 mice after GPI immunization." (PMID 18534002, 2008). "In advanced arthritis, the number of cells with cytoplasmic HMGB1 expression was quantitatively comparable to that of cells expressing TNF and IL-1β." (PMID 17397533, 2007). "The majority of studies of the regulation of cytokines and destructive enzymes in arthritis have relied on the stimulation of outgrown synovial fibroblasts with various catalytic molecules, among them TNF-α and IL-1β." (PMID 17177994, 2006). "In the murine heat-killed S. aureus-induced arthritis model, TNF-α and IL-1β peaked at 2 and 24 hours after the injection of heat-killed S. aureus, respectively." (PMID 17129374, 2006). "To explore the mechanism of the RA and the function of BZXD, we make the collagen-induced arthritis rat and treated with BZXD, then detect the level of TNF-α and IL-1β in plasma at various interval." (PMID 23674954, 2005). "Analyses of both cytokine and chemokine levels in joints from E/P-selectin mutant mice undergoing arthritis revealed elevated production of macrophage inflammatory protein (MIP)-1α and IL-1β compared with wild-type mice." (PMID 16207337, 2005). "In vivo, GHTFs treatment reduced clinical arthritis scores by over 40%, alleviated synovial hyperplasia, preserved collagen volume fraction, and lowered serum levels of TNF-α and IL-1β, demonstrating superior overall efficacy compared to AF and methotrexate (P >0.05)." (PMID 41869362, 2026). "It is reported that NOD-like receptor thermal protein domain associated protein 3 (NLRP3) inflammasome triggered by TGR5-cAMP-PKA axis play a direct role in arthritis inflammation, we therefore further determined the levels of NLRP3, ASC, caspase-1 p20, and IL-1β p17." (PMID 40375326, 2025). "Lactobacillus treatment can prevent the onset of arthritis in preclinical models, reduce arthritis scores in CIA rat and pro-inflammatory cytokines (such as IL-17, IL-1β, IL-6, and TNF-α), and increase the release of anti-inflammatory cytokines like IL-4 and IL-10 in bodily fluids." (PMID 40692793, 2025). "For instance, in a collagen-induced model of arthritis, treatment with a GSK3 inhibitor reduced joint inflammation and leukocyte infiltration and decreased the production of proinflammatory cytokine such as IL-1β, TNF, IL-6, and IFN-γ." (PMID 39923112, 2025). "Interestingly, agents that block IL-1β activity like IL-1β antibodies and the IL-1 receptor antagonist have been described as improving inflammatory diseases such as T2DM, arthritis, gout, and heart failure." (PMID 40149874, 2025).